CXCL10 (C-X-C motif chemokine ligand 10)
Diseases named in the same sentence as CXCL10 in open-access papers (continued):
Sharing a sentence is not in itself a finding about the gene and the disease.
infection (continued). "Furthermore, Mx1 reduces the HSV-1 replication in human fibroblasts, and CXCL10-null mice that are infected with HSV-1 and -2 have reduced numbers of NK and CD8+ T cells at the site of the infection and increased rates of viral replication." (PMID 36423126, 2022). "In contrast, the downregulation of RANTES/CCL5, MIP-1α/CCL3, and MIP-1β/CCL4 from the early to middle phase of the infection as well as the downregulation of MIG/CXCL9, IP-10/CXCL10, and IL-13 in the middle phase of the infection were observed in aged BALB/c mice." (PMID 35264719, 2022). "In the UK study, the MCP-1 levels did not change, and only TNF-α and CXCL10 increased in the infection-primed subjects at 6 days post-vaccination, suggesting a potential polarization towards a Th1 phenotype." (PMID 36119038, 2022). "We observed significant negative correlations between CXCL10 protein concentrations in both supernatant (r = − 0.56, p = 0.01, data not shown) and cell lysate (r = − 0.65, p = 0.002) at 96 h following infection and SARS-CoV-2 replication." (PMID 35484173, 2022). "In this setting, TAT-I24 significantly reduced the transcript levels of Ccl7, Cxcl10 and Ccl5 2 h post-infection, indicating that the inhibitory effect of the peptide is not linked to the reduction of viral gene expression." (PMID 35806257, 2022). "Lenti-Spike infection significantly increased the expression of inflammatory cytokines, including IL-1β, IL-6, and TNF-α, and chemokines, including CCL-2, CCL-3, CCL-4, and CXCL-10, whereas Lipo-hACE2 decoy significantly inhibited all these effects." (PMID 35401811, 2022). "Compared to virulent MERS-CoV-MA-WT and MERS-CoV-MA-mNLS infection, attenuated MERS-CoV-MA-Δ4b induced, either at 4 or 6 dpi, lower levels of CCL2, CCL4 and CXCL10, which are monocyte and macrophage chemoattractants, and CXCL1 and CXCL2, which are neutrophil chemoattractants." (PMID 36129908, 2022). "In addition, the observed effects of different type I IFN subtypes on CXCL10 expression during HIV infection were quite low and the infection kinetics were different for in vitro infections compared to natural infection." (PMID 35911692, 2022). "In addition to CXCL10 and IFN-γ, the mRNA levels of the CCL5 gene also increased in the high-dose group at 4 weeks post-infection (20-fold) and remained at the same level at 7 weeks." (PMID 36051240, 2022). "Together, these data suggest that ferrets infected with a high dose of M. tuberculosis mount stronger pro-inflammatory responses in the lungs in the form of elevated expression of the genes for IL-6, IL-17, CXCL10, IFN-γ, and CCL5, as compared to the medium and low-dose infection groups." (PMID 36051240, 2022). "For HeV, it has very recently been shown that in experimentally infected black flying foxes, viral antigen is detectable in the lungs 60 h post-infection and that there is a considerable increase in type I and II IFN and CXCL10 release in both the lungs and the spleen of these HeV-infected bats." (PMID 35632678, 2022). "For example, heat-iMVA infection triggered higher levels of IFN-inducible genes than MVA, including Ifih1 (MDA5), Ddx58 (RIG-1), Oasl2, Oas3, TLR3, Nod1, Ifna4, Ifnb1, Ccl5, Cxcl9, Cxcl10, and members of the guanylate binding protein (Gbp) family, as largely dependent on STING (marked as b)." (PMID 36261460, 2022). "At 3 day post-infection, higher mRNA levels of C-C motif chemokine ligand 2 (CCL2), C-C motif chemokine ligand 3 (CCL3) and C-X-C motif chemokine ligand 10 (CXCL10) were found in the liver of mice infected with the WT strain as compared to mice infected with the ΔspvB strain." (PMID 33475464, 2021). "Similarly, infection of monocyte-derived macrophages by SARS-CoV in vitro induces expression of CCL2/MCP-1 and CXCL10/IP-10 in an IFN-independent manner." (PMID 34239884, 2021). "infection or transverse the BBB attracted by CXCL9 and CXCL10 during the late stage of infection." (PMID 34587172, 2021).
infection (continued). "In the brainstem, it was observed an increase of pro-inflammatory cytokines, such as IL-1β, IL-12(p70), IL-13, and TNF-α; chemokines, such as CCL2, CCL3, CCL4, CCL11, CXCL10, and CXCL1; growth factors, such as G-CSF, GM-CSF, M-CSF, and anti-inflammatory IL-10 at ten days post-infection." (PMID 33917837, 2021). "The mRNA expression of various inflammatory cytokines (Il-6, Tnf-α, Ifn-γ, and Ifn-β) and chemokines (Ccl2, Ccl4, Ccl12, Cxcl1, and Cxcl10), but not Il-1β, was elevated in the lungs at 2 dpi, in the early stage of infection." (PMID 34463644, 2021). "However, the interferon response (IFNβ1, CXCL10, ISG15, MX1 and MX2) was delayed and increased at 48 h post-infection." (PMID 34452468, 2021). "The production of proinflammatory cytokines CXCL10 and IL-6 increased in both HRV16 and HRV1B infection (p < 0.05 for each), whereas IL-8 and IL-18 production increased in HRV1B infection (p = 0.025 and p = 0.018, respectively), but not in HRV16 infection (p = 0.314 and p = 0.674, respectively)." (PMID 34838080, 2021). "Infection with either virus led to enhanced expression of the inflammatory chemokines CCL5, CXCL10 and CXCL11, whereas mRNA expression levels of IL-6, IL-12 and IL-15 were only increased in MAYV-infected cells." (PMID 33799906, 2021). "However, GEE analyses revealed a marked acceleration of the infection-induced responses measured as the amount of CXCL-8 and CXCL-10 on d3 and d6." (PMID 34959949, 2021). "In addition, ASFV-CN/GS/2018 infection is involved in the regulation of chemokine expression in PAMs, such as CXCL8 and CXCL10." (PMID 34412678, 2021). "Infection of patient PBMCs with SARS-CoV-2 in vitro demonstrated significantly impaired type I and III IFN as well as CXCL10 responses, which may have resulted in impaired ability to clear the infection." (PMID 34625101, 2021). "The production of CXCL10 and CCL8 by latently infected monocytes was confirmed by ELISA; the level of both chemokines in the latently infected CD14+ monocytes were significantly increased over mock and UV inactivated infection controls." (PMID 33912186, 2021). "Infection led to increases in proinflammatory CCL2, IFNγ, IL6 and CXCL10 in wt mice." (PMID 34237114, 2021). "The infection and fatal groups showed considerable increases in several inflammatory factors (gamma interferon [IFN-γ], interleukin 6 [IL-6], IL-8, SIRT2, CCL3, and CXCL10) compared to the control group." (PMID 33593977, 2021). "In fact, fold change of CXCL10 after infection was not under the control of any large effect human genetic variant." (PMID 33106516, 2020). "In addition, both MO-DCs and pDCs produced CXCL10 chemokine on days 4, 9, 12, and 20 after infection, but only MO-DCs produced CXCL9 and CXCL10 at the same time." (PMID 32574175, 2020). "CXCL9, CXCL10, and CXCL11 are chemokines which are able to induce chemotaxis in CD4+ Type-1 helper (Th1) and CD8+ cytotoxic lymphocytes as well as in natural killer cells and natural killer T cells, directing them to sites of infection and inflammation." (PMID 32328494, 2020). "Our main findings were: 1) the host immune response was initiated only in fetuses with detectable levels of PRRSV; 2) upon infection of fetal thymus, a set of core responsive IFN-inducible genes (CXCL10, IFIH1, IFIT1, IFIT3, ISG15, and MX1) were strongly upregulated in both tissues." (PMID 33148169, 2020). "As both CXCL10 and RANTES promote T-cell recruitment to the infection site, we hypothesized that CPAF may suppress RANTES levels similarly to CXCL10." (PMID 33106516, 2020). "In this study, we found that the chemoattractive molecules CXCL10, CCL5, and CCL2 were potently released by the apical compartment upon ZIKV hBLEC infection, suggesting that circulating leukocytes could be attracted to the infected BBB." (PMID 32753493, 2020).
infection (continued). "One study found that, through infection of THP-1- and CD14-positive primary human monocytes, HHV8 upregulates the TLR3 pathway and induces TLR3-specific cytokines and chemokines, including beta 1 interferon (IFN-β1) and CXCL10 (IP-10)." (PMID 33519292, 2020). "Since CXCL10 secretion is induced by IFNγ treatment in a variety of cell types (CXCL10 is also known as interferon-γ-inducible protein 10 or “IP-10”) and T. gondii IST is known to block IFNγ-induced responses during infection, we performed multiple assays with T. gondii strains lacking TgIST." (PMID 32574210, 2020). "An anti-CXCL10 antibody treatment of already diabetic RIP-LCMV mice starting at day 13 after LCMV-infection resulted only in a slight, non-significant reduction by about 25%." (PMID 33193102, 2020). "Additionally, in basolateral infection, we noticed a relative downregulation of many important genes, when compared to apical infection such as CCR1, CXCL10, integrin α5 (ITGα5) and IFNλ-1, -2 and -3." (PMID 32872518, 2020). "An interesting finding that warrants further investigation is the observation that MAVS contributed to CXCL‐10 production in response to infection with DRV‐treated virus, but did not contribute to the corresponding IFIT‐1 reporter activity." (PMID 32852081, 2020). "Cxcl10 expression in the lungs of diabetic mice was lower only during the initial stage of infection compared to non-diabetic infected mice." (PMID 33613280, 2020). "As with HIV‐1 GFP produced in the presence of PIs, infection of PMA‐treated THP‐1 shSAMHD1 cells with the HIV‐1 GFP ∆CA‐SP1 mutants led to a ∆CA‐SP1 dose‐dependent increase in the expression of CXCL‐10 and MxA mRNA, and CXCL‐10 at the protein level." (PMID 32852081, 2020). "This association is completely absent in the C. trachomatis-induced fold change of CXCL10, suggesting that the change in CXCL10 after infection is not significantly explained by regulation through the rs2869462 locus." (PMID 33106516, 2020). "We noticed an increase in CXCL10 and CXCL9 expressions during infection compared to naïve hearts." (PMID 32574175, 2020). "TNF-α, IL-6, CXCL10, and IFN-β were induced after infection with all three viruses." (PMID 32849329, 2020). "Although there was a modest increase of XCL1, CCL2, CXCL2 and CXCL10 mRNAs in these mice following infection, this was not statistically significant." (PMID 32310998, 2020). "Not surprisingly, the induction of CXCL10 occurs almost universally in humans during the course of cell-mediated immune responses evoked in a variety of pathologic states, including infection, allograft rejection, and autoimmunity." (PMID 32089645, 2020). "Furthermore, Ad14p1 infection of the bronchial epithelial cells resulted in increased expression of IL-6 and the chemoattractant chemokines CXCL10 (IP-10) and CXCL11 compared to infection with Ad5." (PMID 32486177, 2020). "As a result, early in infection, innate toll-like receptor (TLR) and PRR signaling pathways continue to potentiate the release of pro-inflammatory mediators, such as cytokines (i.e., TNFα, IL-6, IP10 or CXCL10, etc.)while viral replication remains unchecked." (PMID 32431755, 2020). "While the expression of Cxcl10 and Cxcl11 in C57BL/6 and IL-6−/− mice was similar, it was significantly increased for Cxcl9 in IL-6−/− mice on day 14 and tended to remain higher compared to wild type animals in the further course of infection." (PMID 33375150, 2020). "Specifically, NDDS against SARS-CoV-2 can be designed to interact with viral RNA genome, surface S protein, IL 6, IFN γ-inducible protein 10 (IP-10/ CXCL10), immunoreceptor tyrosine-based activation motif (ITAM) or MCP1, in order to inhibit viral replication and infection." (PMID 33215525, 2020). "The expression of Cxcl10 and Cxcl11 was maximal in both groups on day 21 after infection with Mtb, after which it decreased slowly and was not significantly different at any time point." (PMID 33375150, 2020).
infection (continued). "Furthermore, the ISG IP-10 (CXCL10) was expressed at significantly higher levels during infection with ZIKV-FLA in PNT1a cells, and with ZIKV-FLA or FLR infection in stromal MSCs, over uninfected controls." (PMID 33378361, 2020). "Importantly, CXCL10, CXCL9 and CCL5 were produced throughout the course of infection (until day 120), even when tissue parasitism was low." (PMID 32393333, 2020). "On the basis of all these data, we can hypothesize that subjects infected by P. falciparum must develop an effective immune response by producing chemokines such as IP-10/CXCL10 and inflammatory cytokines such as IFN-γ which can control the infection." (PMID 32801995, 2020). "Induction of MxA and CXCL‐10 (Fig EV1H) expression by LPV‐treated HIV‐1 GFP was severely reduced in the presence of ruxolitinib, indicating that induction of ISG expression in these experiments requires an infection‐driven type I IFN response." (PMID 32852081, 2020). "Gene signatures in the lung of SARS patients indicate that CXCL10, CCL2, interferon-α/β receptor 1 (IFNAR1), Interferon gamma receptor 1 (IFNGR1), and cluster of differentiation 58 (CD58) mRNAs are persistently generated during the infection." (PMID 32365944, 2020). "Only CXCL10 had, on average, a negative fold change after infection of 528 LCLs, and that difference was very close to no change." (PMID 33106516, 2020). "Infection of human cortical collecting duct epithelial cells with BKPyV resulted in downregulation of TNFα expression, but upregulation of the TNF receptors 1 and 2, TLR3, RIG-1, IL-6, IL-8/CXC8, CCL5/RANTES, CCL2/MCP-1, and CXCL10/IP-10." (PMID 31408949, 2019). "In fact, results from a recent study demonstrated that peripheral infection with WNV increased CNS expression of chemokines important for lymphocyte trafficking, including CCL2, CCL7, CXCL9, and CXCL10, in PLX5622-treated mice compared with control-treated mice." (PMID 30704498, 2019). "Amongst cytokines, the genes for Cxcl9, Cxcl10, Cxcl13, Il-1β, Il-6, Tnf, Tnfsf10, IFN-γ, Ccl2, Ccl4, Ccl7, Ccl17, and Mif were highly up-regulated (ranging from 2- to 405-fold, p ≤ 0.05), whereas Cxcl12 and Cxcl14 were down-regulated during in vivo infection." (PMID 30857242, 2019). "This differential modulation of CXCL10 and CXCL8/IL8 may suggest a different role of both chemokines in the infection." (PMID 31619718, 2019). "Interestingly, ISGs, including IFIT2, CXCL10, RIGI, and Mx1, were also detected very early after infection (4 to 12 hpi)." (PMID 31375585, 2019). "In the lungs, the levels of proinflammatory cytokines, including interleukin-1β (IL-1β) and granulocyte colony-stimulating factor (G-CSF), and of chemokines, including IP10/CXCL10, MIP1-α/CCL3, MIP1-β/CCL4, MIP2/CXCL2, and KC/CXCL1, were increased and remained high after the infection with WT cells." (PMID 30940711, 2019). "In addition to enhanced CXCR3 expression, we evaluated the concentrations of the CXCR3 ligands IP-10/CXCL10 and MIG/CXCL9 in the serum of mice at days 0, 6, 8, 10, 12, and 14 after infection." (PMID 31356587, 2019). "We observed secretion of several chemokines in response to T. cruzi infection (CCL2, CXCL5 and CXCL10), which indicate that despite the lack of inflammatory cytokines, the macrophages are not completely immunologically unresponsive to infection." (PMID 31841511, 2019). "Among them, Cxcl1, Cxcl2, Cxcl3, Cxcl10, IL1b, Socs3, and Mmp14 were overexpressed more than 100-fold compared with the non-infected sample regardless of infection type." (PMID 30858471, 2019). "Infection with L. major in a human monocyte cell line induced robust CXCL10 transcription without increasing extracellular CXCL10 protein concentrations." (PMID 31440475, 2019). "In presented study the overexpression of CXCL10 reached the highest level in BOR group and remained at a similar level in both DAN and ILI groups, which corresponds with the most severe clinical outcome of infection observed in BOR-infected pigs." (PMID 29882085, 2018).
infection (continued). "CXCL10 expression is sharply upregulated upon infection and, like fellow chemokine CXCL9, binds receptor CXCR3 expressed on monocytes, NK cells, and T cells to promote their homing to the site of infection." (PMID 30167845, 2018). "Expression of viral RNA, as well as Ccl5 and Cxcl10, but not Tnfα, Il6 Ccl2, Ifna and Ifnb, was significantly decreased in the footpads of Bclx+/- mice at 5 days post-infection." (PMID 30261081, 2018). "Recent extensive studies have indicated that microglia intrinsically produce CXCL10 and CCL5 upon infection with a variety of neurotropic viruses, including cytomegalovirus, human immunodeficiency virus, herpes simplex virus Theiler’s murine encephalomyelitis virus, and Japanese encephalitis virus." (PMID 30001342, 2018). "Regarding the chemokines, diverse studies in humans and mice have indicated that CXCL1, CXCL9, CXCL10, CCL2, CCL3, CCL4, and CCL5 are important in controlling the infection during the acute phase, and the levels of virtually all of them were increased in both BALB/c and C57BL/6 mice." (PMID 29662478, 2018). "Following infection of mice with L. donovani, infected KCs transiently release the chemokines CCL1, CCL2, and CXCL10 in a T cell-independent manner, whereas sustained expression of CXCL10 is dependent upon IFNγ production by invariant NKT (iNKT) cells." (PMID 29636754, 2018). "Chemokines, used to attract leukocytes to sites of infection, were also produced by ZIKV-infected Sertoli cells and RANTES (CCL5), fractalkine (CX3CL1), IP-10 (CXCL10) and GRO (growth related oncogene CXCL1) were found in the supernatant after 46 h of inoculation." (PMID 29751638, 2018). "However, in the 4–99 epg infection group, there was a significant increase in CCL11 (p = 0.002) 3 months post-treatment, whereas, CCL5 and CXCL10 were significantly decreased (p = 0.009 and p = 0.002, respectively)." (PMID 30619332, 2018). "The infection of sham-operated mice with MCMV resulted in the induction of a different chemokine subset containing Ccl12, Ccl7, Ccl4 and Cxcl10." (PMID 29953538, 2018). "Infection of AECs with RSV induces the production of pro-inflammatory mediators, including pro-inflammatory cytokines IL-6 and chemotactic cytokines CXCL8 (IL-8) and CXCL10 (IP-10), which lead to the recruitment of immune cells, including neutrophils." (PMID 29712964, 2018). "IP-10/CXCL10, the cytokine we identify as useful in distinguishing infectious from non-infectious CNS processes, is released from a variety of cell types in response to IFN-γ, a major cytokine in the innate response to infection." (PMID 30379898, 2018). "We confirmed a productive infection of HSV-2 in mouse vagina by immunohistochemistry and immunofluorescence-histochemistry assays, while Cytometric Bead Array (CBA) showed that the production of mouse chemokines CXCL9 and CXCL10 was significantly increased." (PMID 30619292, 2018). "The increased expression of pro-inflammatory interleukins and chemokines (e.g. interleukins, IL-8; IL-7; IL-1β; and C-X-C motif chemokine 10, CXCL10) parallels the transcriptional response of adult frog skin to the chytrid fungus Batrachochytridium dendrobatidis (BD) infection and entry." (PMID 28462779, 2017). "However, gene expression levels of IF1H1, OAS1, IFN-β, CXCL10 and CCL5 were increased in islets following infection with E16 and E30 compared to the mock-infected control." (PMID 28146100, 2017). "The genes with strongest induction included chemokines (e.g. CXCL11, 84-fold; CXCL10, 18-fold; CXCL9, 9-fold; CCL2, 9-fold) and cytokines (e.g. IL6, 54-fold; IL12B, 10-fold; IL1B, 9-fold;) etc. consistent with the infection of host phagocytes with Mtb reported earlier by us." (PMID 28880895, 2017). "In vivo, BALB/c mice were infected and treated or not with CXCL10 (5 μg/kg) at one, three and seven days of infection." (PMID 28767981, 2017).